SNORD99 (small nucleolar RNA, C/D box 99)
Synonyms: HBII-420
Gene: Small nucleolar RNA gene on chromosome 1 (28,578,749 to 28,578,822, reverse strand). Ensembl gene ENSG00000221539.
Gene Ontology:
Biological process: RNA processing
Cellular component: nucleolus
Homologues: Orthologues: macaque SNORD99 (95% identical), rabbit SNORD99 (95% identical), pig SNORD99 (92% identical), mouse Snord99 (91% identical), rat Snord99 (88% identical).
Diseases named in the same sentence as SNORD99 in open-access papers:
SNORD99 is named in the same sentence as 5 diseases in open-access papers, as found by Europe PMC text mining. Sharing a sentence is not in itself a finding about the gene and the disease. The quoted sentences say what the papers report.
hepatocellular carcinoma (1 paper, 2022). A malignant tumor that arises from hepatocytes. "SNORD99, one of the downregulated transcripts in RBPMSA overexpressed clones, was expressed at a higher level in hepatocellular carcinoma patient tissue samples and in the hepatocellular carcinoma cell lines SK-Hep1 and HCCLM9." (PMID 36499073, 2022).
cancer (1 paper, 2022). A tumor composed of atypical neoplastic, often pleomorphic cells that invade other tissues. "Increased levels of SNORD99 have been implicated in the regulation of cell proliferation and death balance by promoting cancer cell plasticity." (PMID 36499073, 2022).
SNORD99 also shares sentences with these, for which no sentence is quoted: lung adenocarcinoma (1 paper); multiple myeloma (1); tumor (1).